CYP27A1 (cytochrome P450 family 27 subfamily A member 1)
Diseases named in the same sentence as CYP27A1 in open-access papers (continued):
Sharing a sentence is not in itself a finding about the gene and the disease.
cerebrotendinous xanthomatosis (continued). "Cerebrotendinous xanthomatosis (CTX) is a rare autosomal recessive sterol storage disease caused by a mutated sterol 27-hydroxylase (CYP27A1) gene." (PMID 26861945, 2016). "Moreover, a mutation of CYP27A1 in humans causes a disease called cerebrotendinous xanthomatosis (CTX), which leads to accumulation of cholesterol in brain and tendons and is accompanied by neurological dysfunctions, including parkinsonism, as well as increased rate of atherosclerosis." (PMID 26480823, 2015). "Two decades after the first report describing defects in sterol 27-hydroxylase as underlying cause of the autosomal recessive disease cerebrotendinous xanthomatosis (CTX), several mutations in the CYP27A1 gene have been described." (PMID 20925952, 2010). "Cerebrotendinous Xanthomatosis (CTX, OMIM 213700) is a rare disease caused by inherited pathogenic variants in CYP27A1 which encodes the sterol-27-hydroxylase enzyme." (PMID 40863986, 2025). "Cyp27A1 mutations in humans lead to the development of cerebrotendinous xanthomatosis (CTX)." (PMID 37349757, 2023). "Cerebrotendinous Xanthomatosis (CTX) is a rare inherited lipid storage disorder caused by deficiency of mitochondrial sterol 27-hydroxylase, related to mutations in the CYP27A1 gene, ultimately leading to an increase of plasma and tissue cholestanol levels." (PMID 38390227, 2023). "Cerebrotendinous xanthomatosis (CTX) is an autosomal recessive disorder caused by pathogenic variants in CYP27A1, leading to a deficiency in sterol 27-hydroxylase." (PMID 37508912, 2023). "Cerebrotendinous xanthomatosis (MIM# 213700) is an autosomal recessive disorder of bile acid and cholesterol metabolism caused by biallelic pathogenic variants in CYP27A1 that codes for the mitochondrial enzyme sterol 27-hydroxylase." (PMID 37564735, 2023). "Cerebrotendinous xanthomatosis (CTX), a rare neurodegenerative disorder caused by autosomal recessive mutations in the CYP27A1 gene, exhibits infantile-onset diarrhoea, juvenile-onset cataracts, young adult-onset tendon xanthomas, progressive neurological dysfunction and so on." (PMID 37308953, 2023). "Cerebrotendinous xanthomatosis (CTX: OMIM#213,700) is a rare autosomal-recessive lipid storage disease caused by deficiency of the mitochondrial cytochrome P 450 enzyme, sterol 27-hydroxylase (CYP27A1, EC 1.14.15.15) due to mutations in the CYP27A1 gene." (PMID 35614401, 2022). "Cerebrotendinous xanthomatosis (CTX) is a rare autosomal recessive lipid storage disease, caused by mutations of the CYP27A1 gene, resulting in deficiency of sterol-27-hydroxylase (CYP27)." (PMID 36238157, 2022). "Cerebrotendinous xanthomatosis (CTX) is a rare autosomal recessive disorder of bile acid synthesis caused by pathogenic variants in the CYP27A1 gene encoding the mitochondrial enzyme sterol 27-hydroxylase." (PMID 33977023, 2021). "Cerebrotendinous xanthomatosis CTX is a neurometabolic storage disorder caused by mutations in the CYP27A1 gene, mapped on chromosome 2q33 and codifying for the 27-hydroxylase, with mutations that lead to reduced enzymatic activity and elevated levels of cholestanol, cholesterol, and bile alcohols." (PMID 33733696, 2021). "Cerebrotendinous xanthomatosis (CTX; OMIM 213700) is a rare, autosomal recessive disorder caused by mutations in CYP27A1, which lead to a deficiency in sterol 27-hydroxylase." (PMID 31863326, 2020). "A defect in the enzyme CYP27A1 leads to the disorder cerebrotendinous xanthomatosis (CTX), where this pathway is inactive." (PMID 31698146, 2020). "More than 30 different mutations in Cyp27a1 cause cerebrotendinous xanthomatosis (CTX) in humans, which is associated with a variety of symptoms including abnormal synthesis of BAs and deposition of cholesterol and its derivatives primarily in the nervous system and tendons." (PMID 31775872, 2019). "Patients with the inherited disease cerebrotendinous xanthomatosis lack the enzyme sterol 27-hydroxylase (CYP27A1)." (PMID 29334954, 2018).
cerebrotendinous xanthomatosis (continued). "Cerebrotendinous xanthomatosis (CTX, OMIM #213700), is a rare autosomal recessive disorder of bile acid synthesis due to variants in the CYP27A1 gene resulting in deficiency of sterol 27-hydroxylase, a key enzyme producing chenodeoxycholic acid (CDCA), which is a primary bile acid." (PMID 38987800, 2024). "Cerebrotendinous xanthomatosis (CTX), first described in 1937, is a rare and often underdiagnosed autosomal recessive lipid storage disease caused by biallelic pathogenic variants of the CYP27A1 gene encoding sterol 27-hydroxylase." (PMID 39717439, 2024). "Cerebrotendinous xanthomatosis (CTX) is a rare inherited disease characterized by sterol 27-hydroxylase (CYP27A1) deficiency and, thus, a lack of bile acid synthesis with a marked accumulation of 7α-hydroxylated bile acid precursors." (PMID 37960277, 2023). "Cerebrotendinous xanthomatosis (CTX; OMIM#213700) is a rare autosomal-recessive inborn disorder of bile acid metabolism due to mutations in the CYP27A1 gene(OMIM *606530) located on chromosome 2q33-qter, leading to increased deposition of cholesterol and cholestanol in multiple tissues." (PMID 25424010, 2014). "Cerebrotendinous xanthomatosis (CTX, MIM: 606530) is a rare autosomal recessive lipid storage disorder caused by biallelic mutations in the cytochrome P450 family 27 subfamily A member 1 (CYP27A1) gene, which encodes sterol 27-hydroxylase." (PMID 41226549, 2025). "Cerebrotendinous xanthomatosis (CTX, OMIM #213700) is a rare inherited metabolic disease caused by the mutation in the CYP27A1 gene." (PMID 38987800, 2024). "Cerebrotendinous xanthomatosis (CTX) is a rare recessive genetic disease characterized by disruption of bile acid synthesis due to inactivation of the CYP27A1 gene." (PMID 36650582, 2023). "Biallelic mutations in CYP27A1 and CYP7B1, two critical genes regulating cholesterol and bile acid metabolism, cause cerebrotendinous xanthomatosis (CTX) and hereditary spastic paraplegia type 5 (SPG5), respectively." (PMID 37024986, 2023). "Also, Cyp27a1−/− mice do not recapitulate all the features of CYP27A1 deficiency in humans and therefore do not develop cerebrotendinous xanthomatosis." (PMID 36914277, 2023). "Cerebrotendinous xanthomatosis (CTX) is an autosomal-recessive lipid storage disorder caused by mutations in the CYP27A1 gene encoding the key enzyme in the bile acid synthesis, sterol 27-hydroxylase." (PMID 35614401, 2022). "Cerebrotendinous xanthomatosis (CTX; OMIM #213700) is an autosomal recessive disorder due to mutations of the CYP27A1 gene, resulting in a deficiency of sterol‐27‐hydroxylase." (PMID 33204601, 2020). "In fact, patients with cerebrotendinous xanthomatosis, lacking of CYP27A1, due to the deleterious effect of gene deletion mutations, present cholesterol abnormally deposited in different tissues, such as vascular endothelium, central nervous system, and crystalline lens." (PMID 29951035, 2018). "We investigated the clinic manifestation, histopathology and sterol 27-hydroxylase gene (CYP27A1) in a Chinese family with Cerebrotendinous Xanthomatosis (CTX)." (PMID 22018287, 2011). "Cerebrotendinous xanthomatosis (CTX) is a rare treatable bile acid disorder caused by homozygous or compound heterozygous variants in CYP27A, a gene that encodes the mitochondrial enzyme sterol 27-hydroxylase (CYP27A1)." (PMID 40731019, 2025). "Cerebrotendinous xanthomatosis (CTX, OMIM 213700) is a rare autosomal recessive condition characterized by disruption of bile acid synthesis due to inactivation of the CYP27A1 gene." (PMID 36650582, 2023). "Cerebrotendinous xanthomatosis (CTX) occurs because cholesterol and cholestanol accumulate in the brain owing to abnormal lipid metabolism and decreased BAs synthesis induced by recessive inheritance of CYP27A1 gene." (PMID 29792192, 2018).
cerebrotendinous xanthomatosis (continued). "Cerebrotendinous xanthomatosis (CTX) is a rare autosomal recessive lipid storage disease characterized by non functioning CYP27A1, resulting in a defective alternative pathway, and abnormal deposition of cholestanol and cholesterol in many tissues, including the central nervous system." (PMID 22343367, 2012). "Cerebrotendinous xanthomatosis develops in the absence of CYP27A1 in humans, while mice lacking CYP27A1 do not develop xanthomas." (PMID 30283400, 2018). "Remarkably, routine MRI revealed unspecific frontotemporal atrophy, but no specific cerebrotendinous xanthomatosis imaging changes, demonstrating that this treatable condition can easily be overlooked in unexplained FTD subjects, even if caused by clearly pathogenic CYP27A1 mutations." (PMID 28749476, 2018).
breast carcinoma (48 papers, 2011 to 2025). "For example, high CYP27A1 expression is associated with a reduced incidence of distant recurrence-free survival events in breast cancer." (PMID 40630116, 2025). "A study found that higher expression of CYP27A1 is associated with a higher grade of breast cancer and lower circulating cholesterol levels, but these changes were not related to prognosis." (PMID 36872411, 2023). "It displayed distinct expression patterns in breast cancer, and a lower expression of CYP27A1 was found to be associated with a shorter overall survival, which was consistent with our findings." (PMID 37817081, 2023). "26-hydroxycholesterol (26-HC) is synthesized by a mitochondrial P-450 enzyme, cytochrome P-450 27A1 (CYP27A1), a gene encoding a cytochrome P-450 oxidase, and is associated with breast cancer etiology, acting in immune cells favoring breast cancer metastasis." (PMID 34571949, 2021). "We observed no statistically significant heterogeneity in associations between circulating 27HC and breast cancer risk by tumor expression of CYP27A1, CYP7B1, LXR-β, or ERβ." (PMID 32075687, 2020). "In contrast to breast cancer, CYP27A1 expression is negatively associated with aggressiveness of prostate cancer; patients whose tumors express higher CYP27A1 mRNA exhibit lower tumor grade and longer disease-free survival." (PMID 30283400, 2018). "Additionally, the regulation of the rate-limiting enzyme CYP27A1 of 27-HA is highly associated with the promotion of breast cancer metastasis." (PMID 38550382, 2024). "However, a study of estrogen receptor positive primary breast cancer showed that high CYP27A1 expression is associated with favorable prognosis." (PMID 36872411, 2023). "We observed limited associations between breast cancer case characteristics and the investigated tumor markers, and no significant heterogeneity in associations between circulating 27HC and breast cancer risk by breast tumor CYP27A1, CYP7B1, or ERβ expression, and limited heterogeneity by LXR-β." (PMID 32075687, 2020). "We observed no significant heterogeneity in associations between circulating 27HC and breast cancer risk by CYP27A1 or CYP7B1 tumor expression though a statistically significant positive association between perimenopausal circulating 27HC and CYP7B1-negative breast cancer risk was observed." (PMID 32075687, 2020). "4T1 cells express Cyp27a1 transcripts, which encode the enzyme responsible for the generation of the oxysterol 27-Hydroxycholesterol (27-HC), and Cyp27a1 protein, as described in other breast cancer models." (PMID 30333826, 2018). "In addition, the expression of CYP27A1 was found to correlate with tumour grade in breast cancer specimens, and in high grade tumours CYP27A1 was expressed in tumour cells and also tumour associated macrophages." (PMID 27068984, 2016). "Elevated expression of CYP27A1 protein was recently observed to be a marker of late lethal disease in a large cohort of breast cancer patients." (PMID 39434198, 2024). "The protein CYP27A1 expression level has been suggested as an important biomarker for postmenopausal breast cancer." (PMID 39434198, 2024). "CYP27A1 is highly expressed in bone marrow immune cells and macrophages and promotes breast cancer by impairing T cell expansion." (PMID 38273053, 2024). "CYP27A1 expression in M2 TAMs is significantly higher than M1 phenotype and can activate M2 TAMs and promote the progress of breast cancer." (PMID 37004014, 2023). "Inhibiting cholesterol conversion to 27-hydroxycholesterol via CYP27A1 has been suggested to prevent breast cancer tumor progression." (PMID 36872411, 2023). "Based on our findings, a poor prognosis for LUAD patients was found to be associated with low expression of CYP27A1, which is consistent with the effect of CYP27A1 on prognosis in breast cancer." (PMID 37817081, 2023).
breast carcinoma (continued). "CYP27A1 was found to be highly expressed in myeloid immune cells and macrophages and played a pro-tumorigenic role in breast cancer by impairing T cell expansion." (PMID 37210507, 2023). "For example, pharmacologic inhibition of CYP27A1 improves the efficacy of anti-PD-1 treatment and decreases metastatic breast cancer growth in mice." (PMID 38023136, 2023). "27-HC synthase CYP27A1 is highly expressed in M2 TAMs derived from breast cancer in mice, whereas the 27-HC catabolic enzyme CYP27B1 is expressed at low levels in tumor cells, leading to the accumulation of 27-HC in tumor tissues." (PMID 37004014, 2023). "The dysregulation of CYP27A1 expression has been found to be a prognostic biomarker in breast cancer, prostate cancer, and ovarian cancer." (PMID 37210507, 2023). "High-grade human breast cancers exhibit high expression of cytochrome P450 27A1 oxidase (CYP27A1), which generates oxysterol 27-hydroxycholesterol (27-HC) from cholesterol." (PMID 34983949, 2022). "Pharmacological inhibition of CYP27A1 prevents 27-HC accumulation and attenuates breast cancer growth." (PMID 34983949, 2022). "CYP27A1, the enzyme responsible for converting cholesterol to 27-OH, was recently explored as a new target for breast cancer adjuvant therapy." (PMID 33676572, 2021). "27-hydroxycholesterol (27HC), synthesized from cholesterol by the enzyme CYP27A1, differentially impacts estrogen receptor positive (ER+) breast cancer (BC) cell growth depending on estrogen levels." (PMID 34556659, 2021). "In human breast cancer tissue, 27OHC concentrations and CYP27A1 protein expression are increased in higher grade tumours." (PMID 35011656, 2021). "In the recent past, a distinct role for cholesterol in promoting ER+ BC progression has emerged in preclinical studies, unraveling the promising connections between 27HC, CYP27A1, and ER+ breast cancer progression." (PMID 33176848, 2020). "This is interesting in light of our previously published work demonstrating that mammary tumor growth was dramatically attenuated by inhibition of the CYP27A1-dependent production of the cholesterol metabolite 27-hydroxycholesterol." (PMID 31164648, 2019). "In this case expression of CYP27A1 in breast cancer tissue would lead to the deactivation of 3β,5α,6β-triol, however, it should be noted that the biological activity of 3β,5α,6β,26-tetrol and its metabolites have yet to be explored." (PMID 29421651, 2018). "CYP27A1 metabolises cholesterol to the ER + breast cancer oncometabolite 26-HC, but CYP27A1 also provides a deactivation rout for 3β,5α,6β-triol diverting its metabolism from the oncometabolite 3β,5α-diHC-6O to bile acid biosynthesis." (PMID 29421651, 2018). "27-OHC administration increases the growth of human breast cancers, and CYP27A1 inhibition suppresses tumor growth in xenograft models." (PMID 30283400, 2018). "Notable was the observation that genetic or small molecule dependent inhibition of CYP27A1 significantly reduced breast cancer colonization of the lungs in two clinically relevant animal models." (PMID 29021522, 2017). "In human breast cancer samples, the expression of CYP27A1, a cytochrome P450 oxidase required for the conversion of cholesterol to 27HC, correlates with tumour grade 93." (PMID 26843513, 2016). "In breast cancer specimens, cholesterol uptake can be converted to 27-hydroxycholesterol (27HC) via CYP27A1, which can lead to tumor metastasis, and tumor growth is also reduced after using CYP27A1 inhibitors." (PMID 40696413, 2025). "Moreover, overexpression of CYP27A1 (sterol 27-hydroxylase), which produces 27-hydroxycholesterol, was reported in patients with breast cancer." (PMID 36479100, 2022). "Thus, both genetic depletion and pharmacological inhibition of CYP27A1 reduce breast cancer metastasis under high-fat-high-cholesterol diet conditions." (PMID 39872079, 2022).